APLN (apelin)
Diseases named in the same sentence as APLN in open-access papers (continued):
Sharing a sentence is not in itself a finding about the gene and the disease.
heart diseases (5 papers, 2010 to 2022). "Studies on animal models particularly in the apelin-knockout mice have evidenced that loss of apelin determines heart diseases in response to pressure overload." (PMID 20671929, 2010). "In addition to promoting heart development, accumulating evidence suggests that ELABELA plays important roles in the cardiovascular system in adults, and is closely linked to some heart diseases that are similar to apelin, another well-known ligand of APJ." (PMID 34384364, 2021).
psychiatric disorder (4 papers, 2018 to 2022). A disorder characterized by behavioral and/or psychological abnormalities, often accompanied by physical symptoms. "We reported for the first time that the APLN rs2235310 and APLNR rs2282623 polymorphisms are associated with the risks of psychiatric disorders in CHD patients and may serve as novel biomarkers for therapy." (PMID 32849850, 2020).
neurological disorders (3 papers, 2022 to 2025). "Apelin signaling is affected by aging, is connected with several neurological disorders, and is neuroprotective in mouse models of PD." (PMID 40360281, 2025). "Apelin plays an important role in various neurological disorders." (PMID 40360281, 2025). "Therefore, targeting the apelin/APJ system can be a promising approach to treating neurological diseases." (PMID 39881878, 2024).
respiratory diseases (3 papers, 2023). "Pulmonary apelin levels are closely associated with respiratory diseases." (PMID 37705751, 2023).
adenocarcinoma (2 papers, 2022). A common cancer characterized by the presence of malignant glandular cells. "The same pattern of expression of apelin and APJ in alpha and beta cells was detected in islets of Langerhans in human adenocarcinoma as well as KC and KPC mouse models." (PMID 36142542, 2022).
infectious disease (2 papers, 2023 to 2024). A disorder directly resulting from the presence and activity of a microbial, viral, or parasitic agent in humans. "In recent years, attention has been focused on specific novel biomarkers such as presepsin, apelin, and irisin due to their potential role in immune response modulation and metabolic regulation in the context of infectious diseases." (PMID 39767230, 2024).
APLN also shares sentences with these, for which no sentence is quoted: pulmonary hypertension (17 papers); essential hypertension (7); acute myocardial infarction (6); hyperlipidemia (5); Huntington disease (4); hypertrophy (4); chronic obstructive pulmonary disease (3); fetal growth restriction (3); gingivitis (3); herpes simplex infection (3); Lewis lung carcinoma (3); malaria (3); Parkinson’s (3); renal failure (3); stable angina (3); acute lung injury (2); advanced heart failure (2); anorexia nervosa (2); aortic aneurysm (2); arrhythmogenic right ventricular cardiomyopathy (2); cervical cancer (2); Chagas disease (2); Cocaine addiction (2); cytomegalovirus infection (2); gastric adenocarcinoma (2); insulinoma (2); Kaposi's sarcoma (2); Metastatic Disease (2); ovarian clear cell cancer (2); ovarian tumor (2).
A further 100 diseases each share a sentence with APLN in 2 papers or fewer.